NEDD8-MDP1 (NEDD8-MDP1 readthrough)
Gene: Protein-coding gene on chromosome 14 (24,213,955 to 24,232,352, reverse strand). Ensembl gene ENSG00000255526.
Genetic constraint (gnomAD): Loss-of-function variants: 13 observed, 29.88 expected, observed/expected ratio (o/e) 0.44, 90% interval 0.28 to 0.69. The upper end of that interval is the gene's LOEUF score, 0.69, which puts it in group 2 of 6, group 1 being the genes least tolerant of losing a copy. Missense variants: 137 observed, 218.8 expected, observed/expected ratio (o/e) 0.63, 90% interval 0.54 to 0.72. Synonymous variants: 84 observed, 77.98 expected, observed/expected ratio (o/e) 1.08, 90% interval 0.9 to 1.29.